BRAF (B-Raf proto-oncogene, serine/threonine kinase)
Diseases named in the same sentence as BRAF in open-access papers (continued):
Sharing a sentence is not in itself a finding about the gene and the disease.
tumor (continued). "After IS-tumor establishment, spheropatients were randomized and treated with a dose of trametinib (1 mg/Kg/die) previously shown to be well tolerated and effective in xenograft models harboring BRAF mutation 37,41." (PMID 33941777, 2021). "In addition, these somatic mutations, especially that of BRAF, are involved in the alteration of the tumor microenvironment through the regulation of the Mitogen-Activated Protein Kinase (MAPK) pathway." (PMID 32392801, 2020). "We analyzed the correlations between the values of SUV and the presence of the BRAF mutation as well with other prognostic factors such as stage, age, specific tumor markers (thyroglobulin and anti-thyroglobulin), extrathyroid extension, the presence of metastatic lymph nodes or distant metastasis." (PMID 32575591, 2020). "Similarly, the repression of COMETT markedly reduces the viability and proliferation of tumor cells harboring BRAF mutation or RET oncogene rearrangement, as well as the motility and invasiveness of tumor cells in vitro." (PMID 33142861, 2020). "Additionally, BRAF V600E mutations are mostly mutually exclusive with most druggable abnormalities present in this tumour." (PMID 31598903, 2020). "In addition, cfRNA was interrogated from an additional five patients who were confirmed to have tumour specific BRAF splicing variants in their progressing tumours." (PMID 33216826, 2020). "In many cases mutant BRAF was also expressed by glial cells, indicating that cells carrying a BRAF mutation remain capable to differentiate into both, neuronal and glial cell lineages, and both of which represent the major cellular composition of the tumor." (PMID 32151273, 2020). "It is important to know tumor genetic profile as genetic mutations have a fundamental impact on the selection of targeted therapy such as BRAF/MEK inhibitors in BRAF-mutated tumors, tyrosine kinase inhibitors in KIT-mutated tumors and MEK inhibitors in NRAS-mutated tumors." (PMID 32637031, 2020). "Notably, all the BRAF mutations, previously detected by SS /Real Time PCR assay/TherascreenTM BRAF Pyro Kit, were confirmed in all tumor samples." (PMID 33317587, 2020). "In addition, HI-511 significantly attenuated tumor growth in the BRAF V600E mutant and PTEN-loss mouse model, which mimics human tumor growth." (PMID 32863956, 2020). "BRAF mutations were detected in 11 (73%) of the 15 tested tumor tissue or urine samples." (PMID 32330187, 2020). "In addition, we found that the size of the largest metastatic focus of LNM negatively correlated with the occurrence of the BRAF V600E mutation in both the primary tumor and LNM." (PMID 33064665, 2020). "Furthermore, our results revealed that poorly differentiated tumor was significantly associated with BRAF status, as well as with advanced age, poor ECOG PS, and lymphovascular/perineural invasion." (PMID 32872561, 2020). "In addition, 12 (12/39; 30.8%) randomly selected cases from VE1-negative tumor samples, were further subjected to the IdyllaTM BRAF mutation test." (PMID 32879641, 2020). "In our cohort, 28 of 83 (34%) patients had BRAF V600Mx, KRAS Mx, NRAS G12/G13 and/or NRAS Q61 mutations in their bone marrow tumor DNA sample (4 [5%] BRAF V600Mx mutations, 13 [16%] KRAS Mx mutations, 3 [4%] NRAS G12/G13 mutations, 14 [17%] NRAS Q61 mutations)." (PMID 32284750, 2020). "Our study showed that BRAF V600E mutation is highly correlated with PTC tumor type (p < 0.001)." (PMID 32393293, 2020). "In addition to tumor cell‐intrinsic consequences of oncogenic BRAF V600E mutation, it has been also implicated in fostering tumor’s immune escape, either by modulating cell immunogenicity or by modulating the microenvironment." (PMID 32330348, 2020). "In addition, we have found an association between KRAS or BRAF mutation status and the differentiation grade of tumors, which suggests a role of these activating mutations in tumor development and progression." (PMID 31952366, 2020).
tumor (continued). "In contrast, TERTp mutations (comparison between BRAF(+)TERTp(+) and BRAF(+)TERTP(−) PTCs) were significantly associated with tumor diameter, invasion of surrounding tissues, pN1b feature, the locally persistent disease after the 1st surgery, and distant metastases." (PMID 32560331, 2020). "Thus, RAF inhibitors selectively block ERK signalling in BRAF-mutant tumours but have the opposite effect in BRAF wild-type cells such as T-cells, where they cause hyper-activation of ERK signalling." (PMID 32753665, 2020). "Also, we observed that the tumor cases with BRAF V600E mutation of ectoderm showed a better survival prognosis than that with the V600E non-mutation (P < 0.001)." (PMID 33308219, 2020). "The most typical molecular alterations associated with the serrated neoplasia pathway could be the mutation in BRAF proto-oncogene and the high level of CpG island methylation phenotype (CIMP-H)." (PMID 32183342, 2020). "Furthermore, the use of BRAF mutation for postoperative analysis using primary tumor tissue is also important to predict the need for radioactive iodine ablation (RAI) therapy." (PMID 33247684, 2020). "Therefore, there is a possibility of improving the outcome of patients carrying KRAS and BRAF mutations by supplementing chemotherapy with ascorbate to maximize the oxidative stress in tumor cells." (PMID 32605263, 2020). "A strong correlation additionally arose between BRAF V600E mutation and tumor location." (PMID 33145020, 2020). "In our patient’s spatially profiled tumor, BRAF amplification compounded by an activating BRAFG421R mutation may have contributed to immunosuppressive MAPK signaling, potentially in conjunction with other chromosome 7 oncogenes." (PMID 32296058, 2020). "However, the development of targeted therapies in tumours with BRAF mutations has revolutionised treatment." (PMID 31599373, 2020). "Given the relative impotence of BRAF fusion to cause neoplasia in other cell types, it would be fascinating to determine whether this genetic alteration is more oncogenic in the cellular context of ventricular zone progenitor cells." (PMID 33206716, 2020). "The most important risk factors for local recurrence have been reported in the literature and are the presence of lymph node metastases, the extrathyroidal extension of the tumor with invasion of perithyroidal tissues, the presence of BRAF V600E mutation, and the incomplete resection of the tumor." (PMID 32585797, 2020). "Common gene variants could be demonstrated in only two out of the six evaluated cases, each presenting with a single gene variant occurring in both tumor foci (BRAF and JAK3)." (PMID 31963551, 2020). "Until approximately 2014, the primary cause of tumor defects in the MMR pathway (other than MLH1 promoter hypermethylation or BRAF V600E mutation) was thought to be LS, and patients were often counseled that they likely had LS even in the absence of a germline PV." (PMID 32973963, 2020). "Presence of a BRAFV600 mutation renders the tumor susceptible to inhibition of the BRAF protein." (PMID 32188904, 2020). "ctDNA BRAF mutation is a prognostic factor of OS and it is correlated with tumor burden." (PMID 32010431, 2020). "Finally, comparing tumor DNA results, 24 patients with BRAF, KRAS and NRAS mutations had shorter survival than 33 patients without these mutations (25 months vs. 61months, P=0.0334)." (PMID 32284750, 2020). "Mitochondrial respiration differs in KRAS, BRAF mutated and wild-type tumor groups, confirming that oncogenes may affect the metabolic requirements of cancer cells." (PMID 32231083, 2020).
tumor (continued). "The BRAF p.V600E mutation was detected in the tumor biopsy for 10 out of the 16 patients." (PMID 32486146, 2020). "The presence of microsatellite instability (MSI) and BRAF V600E mutations also affect the tumor immune milieu and may have influenced the relationship between germline variants and outcomes; this information was not available in the present study." (PMID 33065994, 2020). "For example, BRAF mutations impair antigen presentation in tumor cells, modulate expression of PD‐L1 immune checkpoint molecule, and increase production of cytokines that reprogram tumor‐associated fibroblasts, macrophages, and dendritic cells to exhibit immunosuppressive properties." (PMID 32330348, 2020). "Part of the association of BRAF mutation to the immune response may be linked to MSI, since more than 50% of BRAF mutated tumours are found to be MSI." (PMID 33228141, 2020). "However, the mechanisms governing the WNT pathway activation in the serrated neoplasia pathway, which is uniquely marked by BRAF mutation, is less clear." (PMID 32384699, 2020). "However, in a multivariate model including age, ECOG PS, CCI, primary tumor resected, and stage, only tumor grade (HR = 5.26, 95% CI 1.98–14.01) and BRAF mutation status (3.71, 95% CI 1.07–12.89) were independent prognostic factors for OS." (PMID 32872561, 2020). "In a work published in 2017, on a group of 107 patients the authors concluded that there was a correlation between the value of the SUV and the presence of the BRAF mutation, but in the more advanced tumor it was also correlated with the presence of its extrathyroid extensions and venous invasion." (PMID 32575591, 2020). "However, this procedure has two major shortcomings: (a) it is invasive and thus cannot be used to re-assess or monitor the BRAF gene status overtime; (b) a significant number of mutation-positive patients are missed due to tumor genomic heterogeneity." (PMID 32978468, 2020). "It has been suggested that the type of BRAF-mutation (V600E vs. V600K) influences treatment response: The V600E mutation is more prone to responding to TT, while V600K-mutated tumors typically employ a higher tumor mutational burden and respond better to IT." (PMID 32487100, 2020). "However, one tumor with a wild-type BRAF (P16) was identified with a BRAF mutation in the tumor-derived organoid culture." (PMID 32290033, 2020). "The overall mutation rate of BRAF in malignant tumors is 7% but varies with the tumor type." (PMID 32476297, 2020). "In this group, of the 318 patients who were diagnosed with PTC [including 249 women (78.3%) and 69 men (21.7%), with a mean age at diagnosis of 38±10 years (range, 15–54 years) and a mean tumor size of 1.7±0.8 cm], 232 patients (51.6%) were positive for BRAF-V600E mutation." (PMID 31897179, 2020). "Since the tumor with either KRAS or BRAF mutation has a poor response to anti-EGFR therapy, any mucinous component (more than 5%) may be an adverse indicator for poor responsiveness to anti-EGFR therapy." (PMID 32384877, 2020). "BRAF mutations, either V600E or V600K, identified by standard clinical testing using paraffin-embedded patient tumour tissue, was confirmed in the fresh patient tumour and the corresponding first generation PDX, and identified in all subsequent generations of PDXs." (PMID 31857724, 2020). "Nevertheless, our results strongly support the validity of the scoring system proposed by Niemeier: Our group A tumors are subcapsular (by definition) and strongly associated by multivariate analysis with BRAF V600E, significant fibrosis, intraglandular tumor spread, and lymph node metastases." (PMID 31963890, 2020). "Nonetheless, reports from other countries have demonstrated that tumors with BRAF mutation are associated with tumor location, tumor grade, and mucinous production, our data confirmed BRAF mutations was only association with tumor differentiation." (PMID 32095377, 2020).
tumor (continued). "I-131 adjuvant radiotherapy relies on the uptake of radioactive iodine by tumor cells; therefore, the BRAF V600E mutation may lead to a decrease in the therapeutic effect of iodine-131, resulting in a poor prognosis." (PMID 31949496, 2020). "On some cells, BRAF V600E mutations may induce proliferation initially, but further tumor progression is impeded by MAPK overactivity." (PMID 33348922, 2020). "BRAF mutations were detected in 11 (73%) of the 15 tested tumor samples." (PMID 32330187, 2020). "However, we did not see a clear correlation with specific histotypes, but instead we found an association with tumor genotype showing higher levels of CAFs in BRAF-driven tumors." (PMID 31906302, 2020). "For example, information on clinical features (e.g., ECOG performance status, KRAS/BRAF mutation, primary tumor location) and therapeutic regimens (e.g., FOLFIRI, FOLFOX) given in combination with biological therapy were not available in administrative databases." (PMID 32244478, 2020). "Currently, MEK inhibitors are in clinical trials, in particular for RAS or BRAF mutated tumours." (PMID 31875307, 2020). "Those include subgroup analyses based on specific molecular alterations (eg, certain BRAF mutations), and also more unspecific tumour characteristics such as measures of mutation burden (ie, composite variables of several alterations), tumour grade, or histological subtype." (PMID 32474426, 2020). "One tumor was identified as a KRAS (G12R) co-mutation with BRAF (L567V)." (PMID 32083130, 2020). "In addition, conceivably, the anticipated introduction of universal tumor tissue screening for BRAF-mutations and MMR protein expression for treatment stratification purposes will alter current patient referral patterns, in particular for LS." (PMID 30251116, 2019). "BRAF (V600E) mutation was detected in 28 PTC tumour samples (65.1%)." (PMID 30916170, 2019). "BRAF, another clinically relevant gene, was mutated in one tumour of a pair in 5/23 (22%) cases." (PMID 30894686, 2019). "Finally, to our knowledge, this study provides the first evidence that by using the IdyllaTM Biocartis platform for circulating tumor DNA it is possible to calculate the CMF for those cases positive for RAS or BRAF mutation." (PMID 31597339, 2019). "In our study all 30 cases with BRAF V600E mutation showed unequivocal positive cytoplasmic staining in 85–100% tumor cells; all 30 cases with wild-type KRAS and BRAF were negative; 6.7% (4/60) cases with KRAS mutation showed heterogeneous, cytoplasmic/nuclear staining at stain intensity." (PMID 29127628, 2019). "Indeed, tumor mutational load, in addition to BRAF and CDKN2A alterations are reportedly similar between patients with complete response and those with rapid progressive disease." (PMID 31426590, 2019). "However, when BRAF mutated tumours were considered, the ORR was 41.7% in the HD-FOLFIRI group versus no objective response in the control group (p = 0.003)." (PMID 30585257, 2019). "It is now known that BRAF-mutation positive cancer is a heterogeneous disease, in which the location of the primary tumor may be less important than initially thought, and we hypothesize that focusing on specific alterations may be more important." (PMID 31533235, 2019). "Our data differ from those reported recently, according to which - based on the mutational status in the primary tumor - BRAF- and NRAS-mutant tumors more often develop metastasis to the CNS and liver and NRAS mutant tumors have been associated with lung metastasis." (PMID 31391014, 2019). "Interestingly, increased WNT pathway activation is frequently observed in BRAF-mutated tumours due to loss-of-function mutations in RNF43 —an E3 ubiquitin ligase which mediates ubiquitination and degradation of the WNT receptor complex." (PMID 31412666, 2019). "Within our study cohort, KRAS or BRAF mutations were present in 35 of 65 (54%) tumor specimens." (PMID 31134762, 2019).
tumor (continued). "Tumor location and BRAF Val600Glu mutation status were associated with all outcomes." (PMID 31352904, 2019). "In the present study, even if our results are limited to the techniques used with their analytic sensitivity and complexity, we reported a high level of concordance between plasma and tumor BRAF mutation status in mCRC patients, especially those with liver metastases." (PMID 31319569, 2019). "Tumor PD-L1 expression and BRAF mutation are associated with poor outcomes in patients with NPC." (PMID 31664962, 2019). "Currently, RAS and BRAF mutational testing is carried out from tumor tissue." (PMID 31319569, 2019). "The good prognosis of MSI/BRAF mutated cancers may be related to the increased immune response in MSI tumor." (PMID 31330830, 2019). "The result suggested that the tumor had a BRAF-V600E (COSM476) mutation." (PMID 31340823, 2019). "Indeed, PIWIL1 expression in CRC has recently been correlated with tumor differentiation, infiltration, lymph node invasion, and metastasis and has been tightly associated with BRAF gene mutation (V600E) and poor prognosis." (PMID 31694219, 2019). "Moreover, CRAF hyperactivity was also identified as the mechanism underlying the switching of tumour cells from BRAF to CRAF dependency in preclinical studies." (PMID 31126017, 2019). "Histological and molecular analysis of the tumor indicated the presence of a BRAF V600E mutation." (PMID 30719207, 2019). "Moreover, we found tumors with multiple mutations in the same gene including six tumors with two KRAS mutations, one tumor with three KRAS mutations, and one tumor with two BRAF mutations." (PMID 31036005, 2019). "Like tumor location, BRAF Val600Glu mutation status was associated with all outcome measures." (PMID 31352904, 2019). "BNA-clamp PCR detected BRAF mutations in 6% (3/50) of tumor samples." (PMID 31711486, 2019). "Our model suggest that BRAF mutated tumors may have a higher tumor growth rate than the two other subtypes." (PMID 31076580, 2019). "In BRAF wild type tumours, alternative mutations occurring at NRAS and c-Kit genes must be tested." (PMID 30934988, 2019). "Studies analyzing the association between the mutations status of the tumor and the methylation pattern revealed that BRAF p.V600E, the most common mutation in PTC is associated with increased global hypomethylations whereas RAS mutated tumors have more hypermethylated loci." (PMID 31835496, 2019). "In three of these pairs the tumours shared the same driver mutation either in BRAF, APC, or ACVR2A." (PMID 30894686, 2019). "We posited that a non-linear relationship between gene dosage and fitness under selection may explain the association between BRAF gene amplification, tumor cell fitness and therapeutic resistance to BRAF therapies." (PMID 31723142, 2019). "Tumor BRAF mutations were a poor prognostic factor in both trials." (PMID 31852082, 2019). "Mutations in BRAF have been identified as poor prognostic factors for this tumour type." (PMID 31747973, 2019). "KRAS, NRAS or BRAF mutations had been identified in tumour samples from sixteen of the twenty-four patients (75%), and in twelve of these (75%) the mutation could be verified in the pre-treatment plasma sample by ddPCR." (PMID 31395942, 2019). "The tumour harboured BRAF V600E mutation and a novel germline point mutation in the RET gene, with unknown clinical and pathological meaning." (PMID 31921336, 2019). "It has been observed that BRAFV600E mutations can lead to changes in tumor metabolism, which may be part of the reason for the worse prognosis of BRAF mutations." (PMID 31423225, 2019). "Epithelioid GBM with BRAF V600E mutation can be considered a good treatment indication for precision medicine, and this patient-derived cell line should be useful for prediction of the tumor response and clarification of its biological characteristics." (PMID 31345255, 2019).